TNF (tumor necrosis factor)
Diseases named in the same sentence as TNF in open-access papers (continued):
Sharing a sentence is not in itself a finding about the gene and the disease.
endometriosis (continued). "1,25 (OH) 2D significantly can inhibit interleukin-1β and tumor necrosis factor-α (TNF-α) induced inflammatory responses in human endometriosis stromal cells, and reduce the number of endometriosis stromal cells, thereby improving the symptoms of endometriosis patients." (PMID 38053145, 2023). "The TNFα dependent regulation of the expression of miRNAs associated with endometriosis in eutopic ECs is not well defined." (PMID 37205467, 2023). "The −1031T/C polymorphism in the TNF-α gene reduces the risk of endometriosis, while −238A/G and −174C/G gene polymorphisms in the TNF-α and IL-6, respectively, may increase the risk of endometriosis in Asians." (PMID 37676242, 2023). "In endometriotic cells, NK-κB signaling is activated by TNFα and the aberrant activation of NF-κB signaling leads to chronic inflammation, increased cell proliferation, and survival of ECs in endometriosis." (PMID 37205467, 2023). "Reduced levels of TNF-α in BM may indicate a reduction in the propensity of BM to generate TNF-α producing M1 macrophages that drive endometriosis." (PMID 37545483, 2023). "Curcumin, an antioxidant and anti-inflammatory agent, can reduce the expression of ROS and NO to suppress oxidative stress and inhibit the NF-κB pathway and the expression of TNF-α, IL-1, IL-6, and IL-8 in macrophages of mouse models; thus, it has a potential therapeutic effect on endometriosis." (PMID 36865552, 2023). "In fact, the present study revealed that vaginal mucosa and endometriotic cells responded to increased levels of IL-6, IL-8, IL-1β, and TNF-α when challenged by Candida albicans or by LPS, and these cells present a pivotal role in the inflammatory process in endometriosis and leiomyoma." (PMID 35164046, 2022). "In this way, increased levels of TNF-α, IL-6, IL-8, IL-10, VEGF, and MCP-1/CCL2, as well as different metalloproteinases (MMPs), are associated with the establishment and progression of endometriosis." (PMID 35164046, 2022). "Previous studies have shown that consumption of legumes reduces inflammatory markers such as CRP, TNF-α, IL-6, and other adhesion molecules, as well as the levels of adiponectin that may provide a mechanistic role of legumes in endometriosis." (PMID 36138433, 2022). "Finally, the M1 pro-inflammatory cytokines TNF-α and IL-1β were identified as promising targets in the treatment of endometriosis." (PMID 36555618, 2022). "Endometriosis and AS share the same immunologic characteristics such as TNF-α and Th17 pathway." (PMID 35784295, 2022). "Numerous mechanisms are involved in endometriosis-related pain such as various algogens (pain-producing agents), cytokines (such as IL-1b, IL-6, and TNF-a), growth factors (such as b-nerve growth factor and vascular endothelial growth factor), and several chemokines, such as CCL243,44." (PMID 36266431, 2022). "Interestingly, increases in IL-17A, IL18, TNFSF13B, and TNF signaling have all been previously identified in endometriosis conditions." (PMID 35682747, 2022). "It has been observed that the concentration of TNF-α is elevated in the peritoneal fluid of women with endometriosis and may correlate with the stage of the disease." (PMID 36555618, 2022). "The findings of this study suggest that DNG may reduce cell viability and proliferation in response to treatment with estrogen, TNF-α, IL-1β, or IL-32, and inhibit the pathogenesis of endometriosis by decreasing PCNA expression." (PMID 36428561, 2022). "Additionally, endometriosis patients are found to have elevated levels of proinflammatory factors such as IL-6, IL-8, TNF-α, and prostaglandin E2." (PMID 36361745, 2022). "In addition, the cytokines IL-1α, IL-6, IL-8, IL-18, and TNFα have been found to increase in endometriosis consistently." (PMID 35628423, 2022). "Additionally, PHTPP reduces ERβ expression, which enables the suppression of TNF activity, reducing the onset of endometriosis." (PMID 35885010, 2022).
endometriosis (continued). "In addition, TNF-α was found to contribute to increased gene and protein expression of IL-8 by also stimulating endometriosis-derived stromal cell proliferation." (PMID 35805112, 2022). "In addition, inflammatory cytokine concentrations like IL-1, IL-6, and TNF-α were elevated among endometriosis patients." (PMID 35592328, 2022). "In addition, in patients with endometriosis, B5 derivatives decrease tumor necrosis factor alpha (TNF-α) levels and reduce oxidative stress." (PMID 36687400, 2022). "So, the release of several cytokines related to inflammation, including IL-1β, Cox-2, NF-κb, HIF-1α, TNF-α, IL-6, and IL-8, could modulate proliferation and vascularization followed by endometriosis development." (PMID 35059465, 2022). "Endometriosis patients also display increased IL-1β, IL-6, and TNFα." (PMID 36532015, 2022). "Moreover, elevated serum levels of tumor necrosis factor-alpha (TNF-α), interleukin-1 (IL-1), and interleukin-6 (IL-6) have been found, by some authors, in females with endometriosis." (PMID 34754275, 2021). "Additionally, crocin (25 mg/kg) mitigated VEGF, IL-6, IFN-γ, and TNF-α levels in a mouse model of endometriosis." (PMID 34956439, 2021). "The SRC1-ER complex is suggested to be essential in the early formation of endometriosis as its synergism has been shown to inhibit caspase 8 activation preventing the activation of tumor necrosis factor alpha (TNFα)- induced apoptosis complex II in endometriotic lesions." (PMID 35153815, 2021). "Importantly, miR-125b has been observed to affect the levels of TNF-α, IL-6, and IL-1β, which belong to the group of inflammatory cytokines, and their concentration is elevated in women with endometriosis." (PMID 34201813, 2021). "In endometriosis, TNF Alpha binds to TRADD (tumor necrosis factor receptor type 1-associated death domain protein) that activates the IKK complex and the NF-kB p50/p65 complex involved in gene transcription that regulates gene transcription for innate immunity, inflammation, and cell survival." (PMID 34194730, 2021). "The TNF-alpha level between the endometriotic and non-endometriotic groups were statistically significant, making it a newfound non-invasive diagnostic marker for endometriosis." (PMID 34194730, 2021). "Additionally, it has been observed that estrogen-ER interaction can regulate the production of IL-6 and TNF-α of lipopolysaccharide (LPS) activated pMφ from patients with endometriosis." (PMID 34639133, 2021). "However, our data showed that the production of IFN-γ and TNF-α by CD4+ T cells in the endometriosis group were comparable with that in the control group." (PMID 34531861, 2021). "This cumulative collective evidence could serve as arguments buttressing the idea that peritoneal fluid in women with endometriosis detrimentally effects embryo dynamic due the inflammation induced embryotoxicity -especially by TNF-a." (PMID 33803376, 2021). "Elevated levels of TNF-a, IL-8, and IL-10 are also detected in women with endometriosis." (PMID 33803376, 2021). "Thus, it has been proposed that blocking TNF‐α activity can potentially reduce development of endometriosis." (PMID 34557653, 2021). "IFN-γ, TNF-α, IL-4, and IL-13 are the important cytokines for Th1 and Th2 cells, hence, above results indicated that rhIL-37 maybe improve endometriosis through regulating Th1 and Th2 differentiation." (PMID 34429116, 2021). "Proinflammatory cytokines, such as IL-1, IL-6, and TNF-α, can activate NF-κB, which induces inflammatory cell infiltration and increases the secretion of cytokines, stimulating the NF-κB signaling pathway and forming a positive feedback loop in endometriosis." (PMID 34266426, 2021). "Moreover, macrophages responses to estradiol in the PF of women with endometriosis occurred via in vivo of secrete interleukin-6 and tumor necrosis factor-α." (PMID 33980258, 2021).
endometriosis (continued). "Higher levels of MIP-1α were found in women diagnosed with polycystic ovarian syndrome (PCOS), and the higher levels of IL-23, INF-γ and TNF-α discovered were characteristic of endometriosis while lower levels of IL-β and INF-α were correlated with tubal infertility." (PMID 34833469, 2021). "Previous studies have demonstrated that the levels of pro-inflammatory cytokines IL-6, TNF-α, IL-1β, and IL-17 in the localized lesion (ectopic endometrium and peritoneal cavity) and circulation (serum) were significantly increased in women with endometriosis." (PMID 33815277, 2021). "TNF-α and IL-1β are up-regulated in the peritoneal fluid (PF) of women with Endometriosis causing a decrease in the expression of progesterone receptor type B (PRB) mRNA in endometrial stromal cells isolated from women with Endometriosis." (PMID 33354460, 2020). "Therefore, our finding agrees with previous studies which have recognised the role of TNF in the pathogenesis of endometriosis." (PMID 32121467, 2020). "Endometriosis may decrease steroidogenesis, reduce aromatase activity, alter cell cycle progression, change mitochondrial gene expression, and increase tumor necrosis factor α expression in granulosa cells." (PMID 32151056, 2020). "It is well known that many MMPs and TIMPs are regulated at the transcriptional level by a variety of growth factors, cytokines, and chemokines, and TNFα is involved in the cytokine cascade for the inflammatory response that is considered a key process in pathogenesis of endometriosis." (PMID 32325785, 2020). "Peritoneal macrophages from patients with endometriosis display increased activation of the pro-inflammatory transcription factor NF-κB and enhanced protein expression of pro-inflammatory cytokines such as TNF-α, IL-6, IL-1β, and TGF-β." (PMID 32145751, 2020). "Hence, the present study provides important support for TNF-α in both endometriosis and migraine pathogenesis." (PMID 32121467, 2020). "We show that exposure of ME-SFCs from control subjects to TNF replicates the phenotypes we observed in ME-SFCs from endometriosis patients, including reduced decidualization, reduced expression of ALDH1A1, increased expression of PDPN, and enhanced migration capacity." (PMID 36304708, 2020). "Previous studies report that the eutopic endometrium of patients with endometriosis is in fact different from the eutopic endometrium of controls, with changes in gene expression, and the presence of inflammatory mediators, including TNF." (PMID 36304708, 2020). "Moreover, TNF-α may also play a role in the pathogenesis of endometriosis, as it has been shown that the adhesion of endometrial fibroblast to mesothelial cells is increased in vitro and specific polymorphisms in the TNFα gene are related to the predisposition to endometriosis." (PMID 32325785, 2020). "Thus, these inflammatory factors (IL-6, IL-10, IL-13, and TNF-α) can be used as essential reference indexes for endometriosis diagnosis complicated with infertility." (PMID 33354460, 2020). "Previous studies have showed that IL-1β, IL-6, and TNF-α are increased in women with endometriosis." (PMID 32151056, 2020). "Others factors, like estrogen receptor (ER) alpha, ERbeta, CD68, NCL-MACRO, and HAM56 and inflammatory cytokines IL-1beta, TNF-alpha, and IL-6, as well as pro-inflammatory transcription factor NF-κB are upregulated in macrophages from peritoneal fluid in patients with endometriosis." (PMID 32751735, 2020). "In endometriosis, exosomal miR-138 can protect against inflammation by decreasing the expression level of nuclear factor-κB (NF-κB), a transcription factor that regulates inflammatory cytokines, such as tumor necrosis factor-α (TNF-α) and IL-18." (PMID 31467934, 2019). "Except for TNFα/CCL27 protein ratio that has been consistently reported by the random forest algorithm as the most valuable feature for separating patients with minimal/mild endometriosis from controls." (PMID 31723213, 2019).
endometriosis (continued). "The high level of activate macrophages, prostaglandins, interleukin 1 (IL-1), tumor necrosis factor (TNF) and proteases in the endometriosis may have opposed effects on the ovulatory, sperm, embryo, or fallopian tube, causing infertility." (PMID 31435600, 2019). "For example, levels of pro-inflammatory cytokines IL-1β, IL-6, IL-8, IFN-γ, and TNF-α are elevated in peritoneal fluid and serum of patients with endometriosis and could be used as non-invasive markers of the disease." (PMID 32063886, 2019). "The high level of activate macrophages, prostaglandins, IL-1, TNF, and proteases in the endometriosis could have opposing effects on the evolution of ovulatory, sperm, and embryo causing infertility in endometriosis." (PMID 31435600, 2019). "There is some research showing that the expression of BAFF, TNF-α or IL-6 may be affected in case of endometriosis." (PMID 31088412, 2019). "On the other hand, TNF-α is considered an essential factor in the pathogenesis of endometriosis." (PMID 32063886, 2019). "Concentrations of these molecules were found to be correlated with pain level and stage of endometriosis; in particular, this correlation was positive in the case of increased levels of TNF-α and glycodelin, indicating the potential role of this molecule in the severity of pain in endometriosis." (PMID 32063886, 2019). "The aim was to evaluate the effects of curcumin on growth factors expression by evaluating Growth Differentiation Factor-9 (GDF-9), Kit Ligand (KitL), and Tumor Necrosis Factor α (TNFα) expressions in bovine cumulus-oocyte complexes (COC)s cultured with PF from infertile women with endometriosis." (PMID 31417983, 2018). "The objective of our study was to evaluate whether curcumin could improve growth factors expression in bovine cumulus-oocyte complexes (COC)s by analyzing GDF-9, KitL, and TNFα expressions in culture medium with PF from infertile women with endometriosis." (PMID 31417983, 2018). "In terms of the endometriotic tumor microenvironment, the promotion of tumor invasion via macrophages may be dependent on TNFα, which is elevated in women with endometriosis." (PMID 30087267, 2018). "TNF-α has a major role in the pathogenesis and survival of endometriosis lesions." (PMID 30008440, 2018). "In addition, we found a correlation between TNFα concentration and the degree of endometriosis severity." (PMID 31417983, 2018). "Of a number of proinflammatory cytokines, two have been established as potentially useful for diagnostics, IL-6 and TNF-α, which were found to be correlated with endometriosis and to be effective in diagnosing endometriosis in serum and peritoneal fluid as well as in menstrual effluents." (PMID 28487810, 2017). "Additionally, inhibiting TNF-α reduces embryotoxic effect on mouse embryos incubated with PF from infertile women with endometriosis." (PMID 27740937, 2017). "Unfortunately, it is unclear whether anti-TNF-α therapy reduced disease burden (stage of endometriosis) in women who received these compounds." (PMID 26949527, 2016). "Interestingly, mesothelial cells isolated from the PF of endometriosis patients have been reported to produce IL-8 in response to IL-1α and TNF-α stimulation." (PMID 26247027, 2015). "The inflammatory response in endometriosis may be mediated by proinflammatory cytokines such as tumor necrosis factor-alpha ( TNF-α )." (PMID 26644856, 2015). "Others have also reported higher levels of TNF-α in the endometrium and PF of women with endometriosis but only in mild or early stages of the disease, which suggests that TNF-α plays a role in the early stages of endometriosis when the lesions are establishing." (PMID 26247027, 2015). "Both HIFa and NFκB can be activated by elevated levels of IL-1β and TNFα in endometriosis." (PMID 24927773, 2014). "Recently, a systematic review has concluded that there is not enough evidence to support the use of anti-TNF-α drugs in the treatment of pelvic pain associated with endometriosis." (PMID 25165691, 2014).
endometriosis (continued). "TNFα and oxidative stress in ovarian follicles not only damage oocytes and embryos leading to the impaired fertilization, but also impair endometrial receptivity leading to implantation failure in patients with endometriosis." (PMID 25331066, 2014). "TNFα, which is produced by activated macrophages and NK cells, is a key molecule in endometriosis." (PMID 25331066, 2014). "We can speculate that increased levels of oxidized LDL in the peritoneal cavity of women with severe endometriosis may be one of the factors responsible for increased levels of M-CSF, IL-6, and TNF-α in PF." (PMID 23861560, 2013). "Other proangiogenic factors, namely, IL-8, hepatocyte growth factor (HGF), erythropoietin, angiogenin, macrophage migration inhibitory factor, neutrophil-activating factor, and TNF-α, are all found at increased concentrations in the peritoneal fluid of patients with endometriosis." (PMID 23766765, 2013). "The increased expression of TNFα is consistent with an important role for this cytokine in the early pathogenesis of endometriosis that may be common for different types of lesions." (PMID 24453419, 2013). "A pivotal role of TNFα in endometriosis is corroborated by the finding that TNF-α-targeted suppression by specific drugs inhibits the development of endometriosis in baboons; TNFα has also been shown to be elevated not only in the peritoneal fluid but also in the serum of women with the disease." (PMID 23843796, 2013). "It is possible that this finding simply reflects increased TNF-α serum levels that had infiltrated into the follicular fluid or increased secretion by granulosa cells induced by the inflammatory pelvic milieu in endometriosis." (PMID 22007253, 2012). "Higher follicular MIP-1α and CD44(v6) were found to correlate with polycystic ovary syndrome, IL-23, INF-γ, and TNF-α with endometriosis, higher CD44(v6) but lower IL-β and INF-α correlated with tubal factor infertility, and lower levels of IL-18 and CD44(v6) characterized unexplained infertility." (PMID 22007253, 2012). "Moreover, when compared to TFI patients, women with endometriosis had higher levels of follicular TNF-α (age-adjusted r = 2.6 pg/mL, P = 0.047) and IFN-γ (adjusted by follicular number prior to stimulation r = 16.4 pg/mL, P = 0.030)." (PMID 22007253, 2012). "We observed elevated levels of TNF-α in endometriosis patients, as compared to TFI patients." (PMID 22007253, 2012). "Additionally, gut-derived LPS from Gram-negative bacteria such as E. coli activates Toll-like receptor 4 (TLR4), triggering the increased production of pro-inflammatory cytokines including TNF-α, IL-6, and IL-1β—all of which are elevated in the peritoneal fluid of individuals with endometriosis." (PMID 40430189, 2025). "This hypothesis is supported by a study that shows significant production of IL-1beta, IL-6, and TNF-α in endometriotic tissue and another study that found both basal and stimulated synthesis of IL-6 and TNF-α in peritoneal macrophages of women with endometriosis." (PMID 40507929, 2025). "Moreover, TNF-α is a pro-inflammatory cytokine involved in the development of the ectopic endometrial tissue in the peritoneal cavity and elevated levels of the circulated protein have been correlated with the severity of endometriosis." (PMID 40725086, 2025). "However, yet another study did not confirm the associations between some variants of TNF-α gene polymorphism and the risk of endometriosis in white women." (PMID 40507929, 2025). "Yet another study found that plasma IL-6 levels, but not TNF-α levels, may be useful for differentiating endometriosis from other causes of infertility." (PMID 40507929, 2025). "Moreover, another study found a lack of associations between IL-6 and TNF-α levels and both severity of endometriosis and pain symptoms." (PMID 40507929, 2025). "Thus, EZH2 promotes TNFα-driven inflammation, contributing to endometriosis." (PMID 40630095, 2025).